NF2 (NF2, moesin-ezrin-radixin like (MERLIN) tumor suppressor)
Diseases named in the same sentence as NF2 in open-access papers (continued):
Sharing a sentence is not in itself a finding about the gene and the disease.
malignant mesothelioma (continued). "Genome-wide sequencing analyses of malignant mesotheliomas have revealed frequently observed genomic aberrations such as loss of function mutation and/or copy number alterations/deletion of BAP1, SETD2, CDKN2A, and NF2." (PMID 32545767, 2020). "Case studies have reported WDPMs with somatic mutation of E2F1, heterozygous loss of NF2, and germline BAP1 mutation, which if correct would suggest that they may be variants of malignant mesothelioma." (PMID 32545767, 2020). "The primary objective of this study was to advance our understanding of the malignant mesothelioma TIME while examining the protein expression levels for LAG3, BAP1, NF2, and methylthioadenosine phosphorylase (MTAP)." (PMID 38994676, 2024). "We next investigated the influence of the protein expression of BAP1, NF2, CDKN2A, and LAG3 on the malignant mesothelioma TIME." (PMID 38994676, 2024). "NF2 and LATS2, the upstream components of Hippo pathway, are frequently observed to be inactivated in malignant mesothelioma (MM), leading YAP activation in more than 70% of analyzed primary MM tissues." (PMID 36398861, 2022). "miRNA-615-3p dysregulates CDKN2A, NF2 and JUN in malignant mesothelioma and enhances the phagocytic capacity of splenic macrophages." (PMID 23387986, 2013). "In addition to the immune checkpoint LAG3, BAP1, NF2, and MTAP were chosen as proxies to represent commonly altered TSG products in malignant mesothelioma." (PMID 38994676, 2024). "As mTOR activity is aberrantly upregulated in the case of NF2 inactivation, suppressing mTOR activity by LY3023414 might be considered beneficial for treatment of malignant mesothelioma." (PMID 33660194, 2021). "Indeed, our most important finding is the lack of alterations involving BAP1, SETD2, NF2, CDKN2A, PBRM1, and SMARCC1 genes consistently mutated or deleted in malignant mesotheliomas." (PMID 32545767, 2020). "The WDPMs lacked the alterations involving BAP1, SETD2, NF2, CDKN2A/B, LASTS1/2, PBRM1, and SMARCC1 that are frequently found in malignant mesotheliomas." (PMID 32545767, 2020).
melanoma (26 papers, 2011 to 2026). A malignant, usually aggressive tumor composed of atypical, neoplastic melanocytes. "We found that a decreased Neurofibromin 2 (NF2) mRNA level was associated with a shortened survival in melanoma patients (PNF2 < 5.204 × 10-9)." (PMID 34106558, 2021). "CDKN2A encodes for a cell-cycle regulator mutated in more common cancers like melanoma, and neurofibromatosis 2 (NF2) acts as tumor suppressor that is part of the NF2/Merlin complex that makes up the NF2/Hippo pathway." (PMID 32392897, 2020). "Based on functional annotation and pathway enrichment analysis of DEGs, inflammatory response, immune response, melanoma, and rheumatoid arthritis may be connected with NF2-associated VSs development." (PMID 32733557, 2020). "Although the hallmark of NF2 disease is glial cell tumours, there is increasing evidence that the ubiquitously expressed Merlin protein functions as a tumour suppressor in multiple cell types, including, for example, breast carcinoma and melanoma." (PMID 26258444, 2015). "In addition to these tumor types, NF2 is mutated and/or merlin expression is reduced or lost in numerous non-NF2 associated tumors, including melanoma." (PMID 22912849, 2012). "IHC analysis revealed elevated NF2 expression in melanoma tissues compared with adjacent normal tissues, with higher levels in stage III/IV patients than in stage I/II patients." (PMID 40860143, 2025). "Masson staining indicated that the iEV-150-induced increases in muscle fiber content within melanoma tissues were diminished by NF2 overexpression." (PMID 40860143, 2025). "Our findings demonstrate that iEV-150 efficiently delivers miR-150-3p to melanoma cells, induces ferroptosis via the NF2-Hippo-YAP axis, and reprograms the tumor immune microenvironment (TME) by enhancing CD8+ T-cell infiltration and activation." (PMID 40860143, 2025). "NF2 mutations activate the Hippo/YAP signaling pathway, which has been shown to upregulate PD-L1 expression in tumors like melanoma and lung cancer, potentially making NF2-mutant tumors more immunoevasive." (PMID 41463268, 2025). "Collectively, these results demonstrate that iEV-150 regulates melanoma malignancy and ferroptosis by directly targeting NF2." (PMID 40860143, 2025). "Our study reveals a novel mechanism by which iEV-150 induces ferroptosis in melanoma cells through the NF2-Hippo-YAP signaling axis." (PMID 40860143, 2025). "Small hairpin RNA (shRNA) and genome‐wide CRISPR‐Cas9‐based genetic screenings in melanoma cells, on the other hand, revealed ZNRF3, NF2 and ARIH1 as genes associated with cisplatin resistance." (PMID 40242936, 2025). "While studies in mice support Hippo signaling modulation in NF2-mutant melanomas, studies in humans suggest that NF2-mutant melanomas are more integrally involved in altering the cGas STING signaling pathway." (PMID 39796693, 2024). "In terms of skin carcinomas, melanoma has been verified through several studies to have a link to NF2." (PMID 39796693, 2024). "Previous CRISPR screen of CREs on melanoma cells has been performed on several critical genes, including NF1, NF2, and CUL3, whose loss-of-function mutations resulted in vemurafenib resistance." (PMID 37904237, 2023). "The lentivirus-encapsulated GeCKO library was transfected into melanoma cells, and new melanoma resistance-related genes NF2, CUL3, TADA2B, and TADA1 were identified by vemurafenib resistance screening." (PMID 37834313, 2023). "B16-F1 mouse melanoma cells with kd of Nf2 displayed significantly decreased experimental metastasis in vivo, correlating with reduced sc polarity and transmigration." (PMID 29491397, 2018). "Additionally, NF2 overexpression restored iEV-150-suppressed lung metastasis of B16-F10 melanoma in mice." (PMID 40860143, 2025). "Correlation analysis revealed a negative association between miR-150-3p and NF2 expression in melanoma tissues, whereas survival analysis revealed that high NF2 expression was associated with reduced overall survival." (PMID 40860143, 2025).
melanoma (continued). "To further investigate the role of NF2, we overexpressed NF2 in iEV-150-treated melanoma cells." (PMID 40860143, 2025). "Additionally, the study found that the overexpression of NF2 promotes hydrogen peroxide-induced activation of MST1/2, linking NF2 to the Hippo signaling cascade in melanoma cells." (PMID 39796693, 2024). "In addition, patients with melanoma who expressed lower levels of NF2, TEAD3, and TEAD4 were associated with longer OS than those who expressed lower levels of NF2, TEAD3, and TEAD4." (PMID 38515849, 2024). "Consequently, NF2/Merlin inhibition by phosphorylation of the Rac effector PAK promotes melanoma cell resistance to MAPK inhibitors." (PMID 33072757, 2020). "A CRISPR-Cas9 knock-out screening identified additional candidate genes whose ablation conferred resistance to BRAF inhibitor in melanoma cell line, including neurofibromin 2 (NF2), Cullin 3 E3 ligase (CUL3), and members of the STAGA histone acetyltransferase complex (TADA1 and TADA2B)." (PMID 24743024, 2014). "Moreover, the SP‐01 tumor presents an activating mutation in the ERBB4 gene, which is described as a driver of BRAF wild‐type (WT) melanomas, and SP‐06 presents an oncogenic NRAS mutation, inactivation of NF2, and a truncating mutation in SMARCA4 (in one allele)." (PMID 37798904, 2024). "In NF2-overexpressing melanoma cells cocultured with iEV-150, the results of the EdU and CCK-8 assays revealed that NF2 overexpression counteracted the suppression of proliferation induced by iEV-150." (PMID 40860143, 2025). "GST pulldown and coimmunoprecipitation (co-IP) assays revealed that iEV-150 significantly diminished the physical interaction between NF2 and LATS1 in melanoma cells." (PMID 40860143, 2025). "Further experiments demonstrated that miR-150-3p overexpression suppressed NF2 at both the mRNA and protein levels, whereas ANXA2 overexpression increased NF2 expression in melanoma cells." (PMID 40860143, 2025). "We investigated its mechanism of action, focusing on iEV-150-induced ferroptosis via the NF2-Hippo-YAP signaling axis and its effects on antitumor immunity in melanoma." (PMID 40860143, 2025). "Analysis of the TCGA-SKCM and GTEx datasets revealed elevated expression of NF2, SUZ39H1, CDC25A, GLRX5, and CISD3 in melanoma tissues, in contrast with the reduced expression of VDR, PPARD, CAMKK2, NT5DC2, and CHP1A." (PMID 40860143, 2025). "A high-resolution CRISPR screen of non-coding functional elements surrounding three genes, including NF1, NF2, and CUL3, uncovered several critical CREs that modulate drug resistance in melanoma." (PMID 37904237, 2023). "Exposing transduced BRAFV600E A375 melanoma cells to the BRAF inhibitor vemurafenib yielded enrichment for known resistance gene NF1, as well as a handful of other genes including NF2." (PMID 31921397, 2019). "We therefore performed additional polarity and transmigration assays in three different melanoma cell lines A375, SkMel28 and WM1366 with NF2 kd, demonstrating that the effect of loss of merlin is cell type-dependent." (PMID 29491397, 2018). "AGO2-RIP-qRT‒PCR assays demonstrated that the NF2 and CISD3 mRNAs were markedly enriched in the AGO2-miR-150-3p complex, a finding corroborated by their upregulation in miR-150-3p knockout melanoma cells." (PMID 40860143, 2025). "To further delineate the ferroptosis-modulating effects of this axis, we evaluated melanoma cells treated with the ferroptosis inducer erastin alongside iEV-150, with or without NF2 overexpression." (PMID 40860143, 2025). "Although inhibiting a single target gene, such as ROCK1 and NGFR, can sensitize vemurafenib-resistant melanoma cells, our results showed that pair-wise perturbation of ROCK1 + NF2 or NGFR + NF2 conferred a strong protective phenotype during vemurafenib treatment." (PMID 34106558, 2021).
melanoma (continued). "ARIH1 (Ariadne1 homolog), another ubiquitin ligase, also enhanced cisplatin resistance in normal and melanoma cells by modulating ARIH1, and the tumor suppressor neurofibrillary protein 2, NF2, enhanced cisplatin resistance in melanoma, but not in normal cells." (PMID 38084101, 2023).
lung carcinoma (19 papers, 2020 to 2025). "On the other hand, deep deletion and promoter methylation in LATS1/2, as well as inactivating mutations in NF2 are frequently reported in malignant mesotheliomas, gynaecologic and lung cancers, in congruence with their tumour-suppressive properties." (PMID 34831354, 2021). "NF2 inactivation is known for promoting the development of cancers in the central nervous system but is less frequent in lung cancers." (PMID 40168046, 2025). "To explore YTP activity in such cases, we assessed IAG933 in an NF2-altered PDX model of triple-negative breast cancer (5938-HX) and YTP-75 in a CDX model of NF2-altered lung carcinoma (NCI-H292)." (PMID 38565920, 2024). "They concluded that EVs derived from hypoxia-treated BMSCs facilitate lung cancer progression by delivering miR-328-3p, which targets and inhibits the NF2 gene, thereby inhibiting the Hippo signaling pathway." (PMID 39273095, 2024). "A recent lung cancer transcriptome meta-analysis showed that several HIPPO pathway component (NF2, LATS1, PTPN14, YAP1, TAZ, TAOK, and FAT1) genes were found to fuse in lung carcinoma, and they were independent prognosis factors for low lung cancer survival." (PMID 36147635, 2022). "Consistent with this scenario, NF2 was detected to be down‐regulated in lung cancer cells, which aided in accelerating the proliferation and migration of lung cancer cells." (PMID 33219752, 2021). "Inactivation of NF2 was found to be responsible for refractoriness to erlotinib treatment and progression of lung cancer cells." (PMID 33219752, 2021). "In a recent report, Alcantara and Garcia found that miRNA92a promotes cell proliferation, migration and survival by directly targeting the tumor suppressor gene NF2 in colorectal and lung cancer cells." (PMID 32316543, 2020). "Similarly, miR-328-3p targets the NF2 gene, promoting lung cancer cell proliferation, migration, and epithelial-mesenchymal transition (EMT) by inhibiting the Hippo signaling pathway." (PMID 39273095, 2024). "Results indicated that 4 proteins, MIG6, CD26, NF2, and INPP4B, were directly linked to the lung cancer subtypes and may be useful in guiding therapeutic decision-making." (PMID 38060494, 2023). "Furthermore, we found that, by targeting NF2, which was down‐regulated in lung cancer tissues, EV‐delivered miR‐328‐3p down‐regulated the Hippo pathway to influence the progression of lung cancer." (PMID 33219752, 2021). "In summary, we demonstrated that hypoxic BMSC‐derived EVs could deliver miR‐328‐3p to target the NF2 gene, which inhibited the Hippo pathway, thereby promoting the occurrence and progression of lung cancer." (PMID 33219752, 2021). "Additionally, the expression of miR‐328‐3p and NF2 was detected in lung cancer and adjacent normal tissues." (PMID 33219752, 2021). "However, inactivated NF2 could serve as a bypass mechanism to confer resistance to targeted therapies for lung cancers, including osimertinib, erlotinib, afatinib, and MET TKIs." (PMID 40168046, 2025). "Moreover, miR-328-3p could accelerate the occurrence and progression of lung cancer via NF2-mediated Hippo axis." (PMID 35692583, 2022). "Taken together, our results demonstrated that hypoxic BMSC‐derived EVs could deliver miR‐328‐3p to lung cancer cells and that miR‐328‐3p targets the NF2 gene, thereby inhibiting the Hippo pathway to ultimately promote the occurrence and progression of lung cancer." (PMID 33219752, 2021). "Another study showed that hypoxic bone marrow mesenchymal cell (BMSC)-derived extracellular vesicles could deliver miR-328-3p to lung cancer cells to target the NF2 gene, which ultimately promoted the invasion, migration and EMT of lung cancer by inhibiting the Hippo pathway." (PMID 34659543, 2021). "TAZ-CAMTA1 fusion in epithelioid hemangioendothelioma (EHE), and NF2 deletion in MPM can also predict response to TEAD inhibitors; however, these genetic alterations are extremely rare in lung cancer." (PMID 38499647, 2024).
lung carcinoma (continued). "We observed that the proteins of MIG6, CD26, NF2 and INPP4B were the direct impact factors for the lung cancer subtypes classification." (PMID 38060494, 2023). "Additional gene fusions have also been identified in other vascular and lung cancers involving YAP, TFE3 (transcription factor E3), WWTR1, NF2, LATS1 and LATS2." (PMID 34831354, 2021). "Interestingly, an analysis of 75 different human lung cancer cell lines, including 38 small cell, 34 non-small cell, and 3 carcinoid cell lines, found no NF2 mutants." (PMID 39796693, 2024). "After 6 weeks, enriched sgRNA sequencing was performed in mice with lung cancer metastasis, and several candidate genes related to lung metastasis were identified and verified, including the already known genes PTEN241, miR-345,242 and miR-152243 and several new genes, including Fga, Trim72 and Nf2." (PMID 32296011, 2020).
hepatocellular carcinoma (17 papers, 2012 to 2024). A malignant tumor that arises from hepatocytes. "All mice with NF2 mutations in this study eventually developed both hepatocellular carcinoma and cholangiocellular carcinoma." (PMID 39796693, 2024). "When a mutation in the NF2 gene occurs, tumorigenesis can occur as its tumor-suppressing function ceases, while a splicing form of Merlin promotes hepatocellular carcinoma metastasis." (PMID 37371090, 2023). "NF2 is also infrequently mutated in hepatocellular carcinoma (2%) and intrahepatic cholangiocarcinoma (5%), highlighting NF2’s critical role as a tumour suppressor." (PMID 35119068, 2022). "Deletion of Nf2 in the liver led to substantial liver enlargement and generation of hepatocellular carcinomas (HCCs), intrahepatic cholangiocarcinomas (iCCAs), as well as mixed hepatocellular cholangiocarcinomas." (PMID 37174657, 2023). "Early research in mice suggested that truncation of just one copy of the mouse orthologue, Nf2, was sufficient to induce a spectrum of different cancer types, including osteosarcoma, lymphoma, lung adenocarcinoma and hepatocellular carcinoma." (PMID 35119068, 2022). "In addition to Drosophila, liver-specific conditional knockout of NF2 in mice resulted in increased liver size and a hepatocellular carcinoma phenotype due to inactivation of Hippo signaling and hyperactivation of YAP." (PMID 39160347, 2024). "However, the Cd44 gene status had no influence on either the number of primary liver tumors detected or on the level of the hepatocellular carcinoma biomarker AFP (α-fetoprotein) in the serum of Nf2-mutant mice." (PMID 37174657, 2023). "YAP is also overexpressed in cholangiocarcinoma, cancer of the biliary duct, with increased expression corresponding with a worse patient outcome, in some rare instances due to loss of NF2 function, while YAP promotes therapeutic resistance in in vitro models of hepatocellular carcinoma." (PMID 35119068, 2022). "All mice outliving 30 weeks of age eventually develop either cholangiocellular or hepatocellular carcinoma, suggesting that NF2−/− liver stem/progenitors cells could represent tumor-initiating cells in both neoplasms." (PMID 33925807, 2021). "Suppressing the NF2 gene in the ARID1A mutant background gave iPSCs a growth advantage and, although direct interaction of ARID1A and NF2 is not known, both proteins regulate pathways inhibiting oncogenic YAP/TAZ genes, and their double mutation causes hepatocellular carcinoma in mice." (PMID 37028423, 2023). "In hepatocellular carcinoma (HCC), there are conflicting studies in humans and mice regarding the involvement of Hippo signaling in NF2-mutant tumors." (PMID 39796693, 2024). "Targeted deletion of the Nf2 gene in the mouse liver (albumin-Cre driver specific for hepatocytes and biliary cells) led to increased Yap activation, increased cell proliferation, increased liver size and eventual hepatocellular carcinoma (HCC)." (PMID 26932373, 2014). "Furthermore, contrasting data for Mer/NF2 involvement in developing hepatocellular carcinoma (HCC) and tumors of the bile duct were reported." (PMID 22830020, 2012). "Mice lacking NF2 are prone to develop cancers such as osteosarcoma, lymphoma, lung adenocarcinoma, hepatocellular carcinoma (HCC), and fibrosarcoma." (PMID 33042832, 2020). "Additionally, MORC2 is essential for maintaining cancer stemness, sorafenib resistance and tumorigenesis of hepatocellular carcinoma (HCC) by repressing two critical components involved in the Hippo signaling pathway, NF2 and KIBRA, at the transcriptional level." (PMID 31180332, 2019).